PTPRB (protein tyrosine phosphatase receptor type B)
Diseases named in the same sentence as PTPRB in open-access papers (continued):
Sharing a sentence is not in itself a finding about the gene and the disease.
tumor (33 papers, 2014 to 2026). "PTPRB is a transmembrane protein associated with endothelial cell adhesion, which can inhibit tumor cell proliferation and invasiveness." (PMID 40740229, 2025). "KEGG assays and GSEA assays suggested PTPRB overexpression was associated with several tumor-related pathways." (PMID 34516350, 2021). "In conclusion, our results suggest that miR-624-5p is a negative regulator of PTPRB and a risk factor for tumor metastasis in OS progression." (PMID 31829261, 2019). "As a negative regulator of vascular growth factor tyrosine kinases, PTPRB was found to harbor predominantly truncated mutations in 26% of tumor patients." (PMID 31829261, 2019). "Then, we explored the prognostic value of PTPRB upregulation in CC patients and its potential function in tumor behavior." (PMID 34516350, 2021). "The tumor-related functions of PTPRB on cellular processes of several tumors have been previously reported." (PMID 34516350, 2021). "Functionally, PTPRB knockdown exhibits tumor-suppressive function via reducing cell proliferation and metastasis and inducing cell apoptosis." (PMID 34516350, 2021). "Consistent with mRNA expression, immunohistochemical analysis showed that PTPRB was highly expressed in tumor tissues at the protein level." (PMID 31040266, 2019). "Compared to mice injected with control cells, PTPRB knockdown cells inhibited tumor metastasis in the whole body, such as lung, while PTPRB overexpression increased tumor metastasis." (PMID 31040266, 2019). "Among the candidate genes, we were particularly interested in PTPRB due to its potential tumor-suppressing role in carcinogenesis and cancer development." (PMID 31829261, 2019). "The COX proportional hazard model demonstrated that doubled expressions of three genes, i.e., CREB5, PTPRB and COL4A3, was associated with 63% to 97% decreased risk of death, recurrence or progression, suggesting their potential role as tumor suppressors." (PMID 25105010, 2014). "Recently, it has been found that PTPRB may function as a tumor suppressor in tumorigenesis and development." (PMID 35311113, 2022). "In addition, in several tumors, functional assays have been applied to demonstrate the tumor-related effects of PTPRB on tumor progression." (PMID 34516350, 2021). "Moreover, tumor sections from PTPRB knockdown xenografts showed lower levels of vimentin expression and upregulation of E-cadherin expression." (PMID 31040266, 2019). "Moreover, western blot analysis and RT-PCR revealed that PTPRB knockdown decreased vimentin expression and increased E-cadherin expression in tumor tissues." (PMID 31040266, 2019). "Our results suggest that PTPN12 may phenocopy the tumor suppressor role of PTPRB in murine endothelial cells." (PMID 29872503, 2018). "PTPRB could catalyze the dephosphorylation of phosphotyrosine residues, and along with protein tyrosine kinases could modulate the levels of phosphotyrosine modification in tumor cells." (PMID 31040266, 2019). "Hence, PTPRB could regulate the proliferation, migration, invasion, and tumorigenesis of tumor cells as an essential regulator of the RTK signaling network." (PMID 31040266, 2019). "Exome sequencing identified unique variants in AA patient samples within key genes, including TP73 (tumor suppression), XYLB (metabolism), ALDH4A1 (oxidative stress), PTPRB (cellular signaling), and HLA-DRB5 (immune response)." (PMID 40104216, 2025). "Quantitative real-time PCR (qRT-PCR) exhibited that expression of CPS1 and PTPRB was downregulated in tumor tissues compared with paracancerous tissues, while MAP2, DYNC1H1, and MKI67 were overexpressed in tumor tissues." (PMID 35311113, 2022).
tumor (continued). "The expression of MAP2, DYNC1H1, and MKI67 was obviously higher expressed in tumor tissues, while CPS1 and PTPRB were downregulated in tumor tissues compared with normal tissues in TCGA dataset." (PMID 35311113, 2022). "Overall, PTPRB is highly expressed in CC and can effectively enhance the proliferation, metastasis and EMT process of tumor cells." (PMID 34516350, 2021). "The in vitro experiments showed an antimetastasis role of PTPRB knockdown in CRC, and thus prompted us to evaluate its functions in tumor metastasis in vivo." (PMID 31040266, 2019). "PTPRB knockdown decreased the number of invasive CRC cells in an in vitro wound healing model, and also reduced tumor metastasis in vivo." (PMID 31040266, 2019). "We found that the expression level of PTPRB was negatively correlated with TNM stage, tumor size, and lung metastasis." (PMID 31829261, 2019). "The cell type-specific markers we used for cell annotation were as follows: T cell (CD3D); NK cell (KLRD1 and NKG7); plasma cell (IGKC and JCHAIN); Mast cell (KIT and TPSB2); tumour cell (CA9, NDUFA4L2 and SLC17A3); endothelium (PECAM1, PTPRB and KDR); mesangial cell (ACTA2 and PDGFRB)." (PMID 40830065, 2025). "In addition, we observed that tumours with RS4 had an increased frequency of SVs in genomic regions containing MDM2, H3F3B, PTPRB and GRM3 compared to tumours devoid of RS4." (PMID 35396535, 2022). "Recurrent PTPRB and PLCG1 mutations have been previously reported in this tumor type; however, no somatic coding mutations affecting either gene were found in our data set." (PMID 28056866, 2017). "However, its tumor-related effects and prognostic values of PTPRB in CC have not been investigated." (PMID 34516350, 2021).
cancer (25 papers, 2017 to 2025). A tumor composed of atypical neoplastic, often pleomorphic cells that invade other tissues. "We labeled cell types as endothelial cell (Endothelial, gene expression of PLVAP, KDR, PTPRB) and cancer associated fibroblasts cell (CAFs, gene expression of FAP, MMP11, PDGFRB, SFRP2, PDGFRA, ADAMTS2)." (PMID 37065499, 2023). "PTPRB, encoding a protein tyrosine phosphatase, regulates critical signaling pathways that influence growth factor signaling, cell cycle progression, and migration—key processes in cancer metastasis and progression." (PMID 40104216, 2025). "PTPRB can be inactivated in human cancers through genetic mutations." (PMID 34582677, 2021). "CD36, THBS1, and PDK4 were highly expressed in cancer tissues, whereas PTPRB, G3BP2, and TMEM125 were lowly expressed in cancer tissues." (PMID 36147333, 2022). "G3BP2 and PTPRB are lowly expressed in cancer and are reliable markers for prognosis of patients." (PMID 36147333, 2022). "Recent studies have shown that PTPRB may exert an effect on carcinogenesis and cancer development." (PMID 31829261, 2019). "CD36, PDK4, and THBS1 were highly expressed in cancer tissues, and G3BP2, PTPRB, and TMEM125 were lowly expressed in cancer tissues." (PMID 36147333, 2022). "Among pan cancer drivers, EP400 was detected in three individuals, and both synonymous and non-synonymous alterations in the genes AMER1 and PTPRB were detected in two cohort members." (PMID 34016182, 2021). "We identified 35 genes that were more frequently altered in HS/CB tumors versus corresponding TCGA cohorts; of which, 8 genes (PREX2, BIRC6, CNTNAP2, PTPRB, GRM3, ANKRD11, BRCA2, and TET3) are listed on the OncoKB Cancer Genes catalogue." (PMID 34446728, 2021).
PTPRB also shares sentences with these, for which no sentence is quoted: diabetes (8 papers); infection (7); macular edema (4); atherosclerosis (3); diabetic nephropathy (3); Hypertension (3); autoimmune disease (2); breast carcinoma (2); ocular hypertension (2); retinopathy (2); acute respiratory distress syndrome (1); bacterial infections (1); brain tumors (1); cervical cancer (1); diabetic eye disease (1); endothelial dysfunction (1); endotoxemia (1); epilepsy (1); glioma (1); Graves disease (1); hyperlipidemia (1); Insulin resistance (1); ischemia (1); macular degeneration (1); metastatic melanoma (1); metastatic tumours (1); neurodevelopmental disorder (1); neurological disorders (1); Obesity (1); ovarian carcinoma (1).
A further 11 diseases each share a sentence with PTPRB in 1 paper.